C3orf62 (chromosome 3 open reading frame 62)
Description:
Essential for normal spermatogenesis and male fertility.
Synonyms: FLJ43654; MAPS
Tractability: No criterion of Open Targets' tractability assessment is met for any kind of drug.
Gene: Protein-coding gene on chromosome 3 (49,268,596 to 49,277,232, reverse strand). Ensembl gene ENSG00000188315.
Subcellular location (Human Protein Atlas): Nuclear speckles
Gene Ontology:
Molecular function: protein binding
Biological process: spermatogenesis
Genetic constraint (gnomAD): Loss-of-function variants: 16 observed, 20.74 expected, observed/expected ratio (o/e) 0.77, 90% interval 0.52 to 1.17. The upper end of that interval is the gene's LOEUF score, 1.17, which puts it in group 5 of 6, group 1 being the genes least tolerant of losing a copy. Missense variants: 297 observed, 323.73 expected, observed/expected ratio (o/e) 0.92, 90% interval 0.83 to 1.01. Synonymous variants: 114 observed, 122.45 expected, observed/expected ratio (o/e) 0.93, 90% interval 0.8 to 1.09.
Homologues: Orthologues: chimpanzee C3H3orf62 (98% identical), macaque C2H3orf62 (95% identical), dog C3orf62 (84% identical), pig C3orf62 (82% identical), rat C8h3orf62 (76% identical), mouse 1700102P08Rik (75% identical), rabbit C3orf62 (71% identical), guinea pig C3orf62 (54% identical).
Diseases named in the same sentence as C3orf62 in open-access papers:
C3orf62 is named in the same sentence as 8 diseases in open-access papers, as found by Europe PMC text mining. Sharing a sentence is not in itself a finding about the gene and the disease.
C3orf62 shares sentences with these, for which no sentence is quoted: aneurysm (1 paper); breast carcinoma (1); breast tumor (1); cancer (1); cardiovascular disease (1); cervical cancer (1); infection (1); lupus (1).